VIM (vimentin)
Diseases named in the same sentence as VIM in open-access papers (continued):
Sharing a sentence is not in itself a finding about the gene and the disease.
mesothelioma (27 papers, 2003 to 2025). A usually malignant and aggressive neoplasm of the mesothelium which is often associated with exposure to asbestos. "Because most cancers are typically labeled positively by either pan-cytokeratin or vimentin alone, positive staining with both markers often provides an initial clue for the potential diagnosis of mesothelioma." (PMID 38026668, 2023). "A diagnosis of mesothelioma typically involves positivity for both cytokeratin and vimentin markers." (PMID 38105775, 2023). "Mesotheliomas are positive for both cytokeratins and vimentin, while carcinomatosis lesions are only positive for cytokeratins, and sarcomatosis only for vimentin." (PMID 36290171, 2022). "PM cells, referred as PM27 in the present work, express mesothelin, vimentin and keratin 5, considered as typical markers of mesothelioma." (PMID 30651596, 2019). "IHC (immunohistochemistry) shows the presence of both cytokeratin and vimentin, suggesting the diagnosis of mesothelioma." (PMID 31470859, 2019). "The morphology combined with staining for vimentin and pancytokeratin is consistent with a sarcomatoid mesothelioma." (PMID 25877069, 2015). "However, immunohistochemical analysis revealed a profile of vimentin positivity, cytokeratin negativity, and Iba-1 negativity, effectively excluding mesothelioma and histiocytic sarcoma." (PMID 41375544, 2025). "Tumours of approximately equal size arising in lenti-Cre induced mice with and without asbestos were compared by IHC for expression of cell lineage markers (pan-cytokeratin, vimentin and smooth muscle actin) along with Ki67 and the commonly used mesothelioma markers WT1 and Mesothelin." (PMID 37441092, 2023). "All presumptive sarcomatous mesotheliomas stained positively for podoplanin and vimentin." (PMID 24405760, 2014). "Therefore, the author aimed to discover whether the observed cells were reactive mesothelial, mesothelioma, or adenocarcinoma cells through immunocytochemistry using five markers (cytokeratin, vimentin, desmin, E-cadherin, and calretinin) in a canine patient." (PMID 37480011, 2023). "Therefore, the author aimed to discover whether the observed cells were reactive mesothelial, mesothelioma, or adenocarcinoma cells via immunocytochemistry using five markers (cytokeratin, vimentin, desmin, E-cadherin, and calretinin)." (PMID 37480011, 2023). "The most common markers included calretinin, CK5/6, WT-1, D2-40, Vimentin, HBME-1, ER, PR, CEA, Ber-EP4, B72.3, and HNF-1β, and the first six were mesothelioma markers with high sensitivity." (PMID 39605894, 2024). "What is more, incubating mesothelioma cells with senescent mesothelioma cells media (the senescence inducer was chemotherapeutic—pemetrex) leads to enhancement of EMT hallmarks, for instance vimentin upregulation." (PMID 36232388, 2022). "In human mesothelioma cases, CAM5.2 and AE1/AE3, both of which are usually used as the epithelial markers, are expressed in the sarcomatoid type, and vimentin, which is one of the mesenchymal markers, is expressed in the epithelioid one." (PMID 32677949, 2020). "The neoplastic cells were positive for vimentin but negative for cytokeratin and Iba-1, ruling out both mesothelioma and histiocytic sarcoma." (PMID 41375544, 2025). "Immunohistochemically, mesothelioma usually positive for CK, Vimentin, Calretinin and CK5/6, and negative for CEA, while adenocarcinoma of the rete testis is usually positive for CK, and negative for CK5/6." (PMID 23800084, 2013). "This cell line was obtained from a confirmed human mesothelioma case and exhibited both the ultrastructural features and immunocytochemical characteristics of mesothelial cells based on coexpression of cytokeratin and vimentin, and absence of carcinoembryonic antigen expression." (PMID 12569381, 2003).
mesothelioma (continued). "According to immunohistochemical analysis, SFT of the pleura is positive for vimentin, CD34, CD99, and Bcl2, which are markers of mesenchymal cells; but it is negative for cytokeratin, which is found in mesotheliomas." (PMID 21958732, 2011).
mesenchymal tumor (26 papers, 2010 to 2026). "Again, we observed that low EpCAM expression was associated with high vimentin expression, suggesting that capture of mesenchymal tumors may be challenging with EpCAM based-methods and that other capture antibodies may be required to capture the full range of CTCs." (PMID 20838621, 2010). "Histopathological examination revealed an undifferentiated malignant mesenchymal tumor, positive for vimentin, with a Ki-67 proliferation index of approximately 30%." (PMID 41535877, 2026). "VIM is considered a key intermediary filament of fibroblasts that interacts with the actin cytoskeleton and modulates the invasion of mesenchymal tumors." (PMID 37766348, 2023). "These are aggressive mesenchymal tumors and are devoid of the major known biomarkers except vimentin." (PMID 32652895, 2020). "On histopathology, we found malignant mesenchymal tumor positive for vimentin and cluster of differentiation 10 (CD10)." (PMID 31523571, 2019). "In general, although carcinomas express CK and mesenchymal tumours express vimentin, the exceptions to that rule must be remembered." (PMID 29808414, 2018). "All the PIWIL2-GFP fibroblasts derived tumors tested stained positive for the transfected gene, PIWIL2, as well as VIMENTIN (marker of mesenchymal tumors), Synaptophysin (SYN, markers of neurogenic tumors) and NESTIN." (PMID 28103575, 2017). "IHC is used to differentiate gastric schwannoma from other GI mesenchymal tumors; gastric schwannoma strongly and diffusely stains positive for S100, vimentin, and glial fibrillary acidic protein (GFA) and is consistently negative for CD117, DOG -1, CD 34 and smooth muscle actin (SMA)." (PMID 39027743, 2024). "Vimentin is a marker for mesenchymal cells, which is positive in mesenchymal tumors." (PMID 39564019, 2024). "Finally, the vimentin staining and the microscopic appearance of malignant cells led to the diagnosis of malignant mesenchymal tumor." (PMID 39420880, 2024). "Vimentin is a mesenchymal tumor marker with high sensitivity and specificity and can be used in conjunction with CK to distinguish between most epithelial and mesenchymal tumors." (PMID 38968487, 2024). "The cytokeratin-positive immunoreactivity in the tumor cells was demonstrated in all the epithelial tumor cases by IHC, and the vimentin-positive immunoreactivity in the tumor cells was also demonstrated in the mesenchymal tumor and melanocytic tumor cases by IHC." (PMID 36851457, 2023). "Positive findings of CD34 and vimentin only indicate a mesenchymal tumor." (PMID 27044420, 2016). "Pan-Cytokeratin (CK, an epithelial tumor cells marker), vimentin (a marker of mesenchymal tumor), α-actin (a marker of myogenic tumor), CD31 (a marker for vasculogenesis), NF-M and GFAP (markers of neurogenic tumor) were used to stain the tumors (data not shown)." (PMID 22511923, 2012). "AMFs are characterized by the expression of vimentin, desmin and CD34, suggesting an undifferentiated mesenchymal tumor with preferential myofibroblastic differentiation." (PMID 24894537, 2014). "The HC-AFW1 cell line also expressed epithelial cell markers such as E-Cadherin, CD326 and cytokeratins as well as Vimentin, CD44 and CD133, proteins that are often found in epithelial and mesenchymal tumours." (PMID 22666492, 2012). "In the third category there were seven studies on epithelial mesenchymal transition (EMT)/TGFb/mesenchymal tumor (EMT/TGFb/Mes) according to the authors, with specific genes CDH1,2, VIM, and TGFb1,2,3 in studies as follows: E16 (CDH1,2, TGFb1, VIM), E24 (TGFb1), E31, E38, E39, E43 (CDH2), and E46." (PMID 40867621, 2025). "PANC1 cells grown in conditioned media also showed a decrease in the expression of E-cadherin (CDH1) and an increase in expression of zinc finger E-box binding homeobox 1 (ZEB1) and vimentin (VIM), pointing to a PAR1/macrophage-induced mesenchymal tumor state in PDAC." (PMID 34066284, 2021).
mesenchymal tumor (continued). "Desmin, vimentin, and calretinin are characteristic immunohistochemical markers of mesenchymal tumours which were negative in our case on IHC." (PMID 27034865, 2016). "Because SFT is a mesenchymal tumor, immunohistochemical staining is positive for CD34 and vimentin, and negative for mesothelial cell-derived cytokeratin and epithelial membrane antigen." (PMID 33188464, 2020).
autoimmune disease (25 papers, 2006 to 2025). A disorder resulting from loss of function or tissue destruction of an organ or multiple organs, arising from humoral or cellular immune responses of the individual to their own tissue constituents. "This protein complex included the protein vimentin and it has been studied that its dysregulation is associated with several cancers and autoimmune diseases." (PMID 39997396, 2025). "Citrullinated vimentin has been linked to several chronic and autoimmune diseases, but how citrullinated vimentin is associated with disease prevalence and genetic variants in a clinical setting remains unknown." (PMID 38155185, 2023). "Blocking/cleavage of extracellular pathological forms, and overexpressing cell surface forms of vimentin by decoy peptides or antibodies can be one of the strategies to target vimentin in lung diseases such as autoimmune diseases, cancer, and infections." (PMID 35573702, 2022). "Antigenic hallmarks of vimentin, among other recognized autoantigens in autoimmune diseases, are exacerbated by post translational modifications, specifically citrullination." (PMID 33043033, 2020). "Vimentin is required for a proper immune response, but it can also act as an autoantigen in autoimmune diseases or as a damage signal." (PMID 32630064, 2020). "The following subject terms were used in the search: Citrulline, Citrullination, Anti-CCP, PAD, Peptidylarginine deaminase, antimutated, antimodified vimentin, autoimmune disorders, Saudi Arabia, or combined autoimmune disorders, Saudi Arabia." (PMID 31886309, 2019). "In pathological conditions such as inflammation, tissue injury, or autoimmune disease, vimentin undergoes posttranslational modifications (PTMs) including phosphorylation and citrullination, which promote the disassembly of vimentin filaments into soluble oligomers." (PMID 40346842, 2025). "Intriguingly, sarcoidosis has even been suggested to be an “autoimmune disorder” considering the evidence of in situ recognition of vimentin by both T- and B-cells in HLA-DRB1*03+ sarcoidosis patients, associated with the detection of anti-vimentin antibodies in BALF." (PMID 39062076, 2024). "Citrullination occurs on extracellular vimentin through peptidyl arginine deiminases, converting arginine to citrulline which may result in autoimmune diseases as the immune system tags the vimentin as foreign." (PMID 36230521, 2022). "Notably, citrullination of cytoskeletal proteins such as vimentin, fibrin, collagen II and filaggrin has been reported in various autoimmune diseases." (PMID 36401289, 2022). "Interestingly, vimentin, usually modified by citrullination, and likely by other modifications such as oxidation and/or proteolysis, becomes an autoantigen in autoimmune disease." (PMID 32630064, 2020). "There are many autoimmune diseases that involve the presence of autoantibodies against vimentin." (PMID 32630064, 2020). "Anti-vimentin auto-Abs (AVA) are described in a number of autoimmune diseases." (PMID 25374567, 2014). "Presence of autoantibodies in autoimmune diseases such as RA has been reported in 40% RA patients' sera, and such antibodies can direct actions against the Sa antigen presence on the surface of citrullinated vimentin." (PMID 23781264, 2013). "However, given the presence of a humoral response to modify citrullinated vimentin in a number of autoimmune diseases, the presence of antibodies against vimentin in patients with sarcoidosis does not serve as a diagnostic marker for this pathology." (PMID 39598118, 2024). "Molecular mimicry plays an important role in autoimmune diseases, and it was initially indicated after finding cross-reactivity of the phosphoprotein of the measles virus and a protein of the herpes simplex virus type 1 with an intermediate filament protein (vimentin) of human cells." (PMID 36560940, 2022).
autoimmune disease (continued). "To date, our antibodies are unique in discriminating native LL37 from cit-LL37 and the demonstration that they do not recognize ubiquitously expressed autoantigens, such as vimentin and enolase, suggests their use in autoimmune diseases, particularly in RA." (PMID 32403306, 2020). "Coincidently, vimentin and other proteins specifically upregulated at day 1 pi with E75CV1, such as HSPB1, enolase or LCP-1, share both their potential role in immune defense and their description as autoantigens in autoimmune disorders." (PMID 30208957, 2018). "However, the presence of serum vimentin autoantibodies could not be considered pathognomonic of sarcoidosis disease, due to their presence in several autoimmune diseases, such as systemic erythematous lupus, antiphospholipid syndrome, and rheumatoid arthritis." (PMID 36148452, 2022).
schwannoma (25 papers, 2008 to 2026). A benign, usually encapsulated slow growing tumor composed of Schwann cells. "Schwannoma cells are positive for S100 protein, a family of low‐molecular‐weight proteins expressed by neural crest‐derived cells, as well as vimentin, an intermediate filament protein found in mesenchymal cells." (PMID 41497769, 2026). "Immunohistochemistry shows a sensitivity of schwannomas to S-100 and vimentin stains, which are proteins prevalent in Schwann cells." (PMID 40486271, 2025). "Immunohistochemical analysis of schwannoma cells shows positive staining for S-100 and vimentin, both of which are known to be present in Schwann cells." (PMID 40486271, 2025). "Histology showed palisade spindle cells, and immunohistochemistry was positive for S-100 protein and vimentin, confirming a diagnosis of schwannoma." (PMID 40507589, 2025). "Immunohistochemical markers including CD117, CD56, CD34, S100, SOX10, Calretinin, Desmin, Vimentin, EMA and smooth muscle antigen are associated with Schwannomas and can be used to confirm their diagnosis." (PMID 39558963, 2024). "Vimentin, a marker of mesenchymal origin, was positive in all the schwannomas, with weak (n = 3), moderate (n = 1), or marked (n = 6) reaction in 55–100% of the cells (mean value of 90%)." (PMID 39451657, 2024). "IHS for MPNST would stain positive for vimentin (indicating mesenchymal origin), with possible S-100 positivity, indicating the malignant transformation of schwannoma." (PMID 36514670, 2022). "The S-100 protein and NSE stained positively in all Schwannomas; Vimentin presented negativity in 3 (21.4%) patients and positivity in 11 (78.6%) patients; GFAP presented negativity in 1 (33.3%) and positivity in 2 (66.6%) patients." (PMID 30710876, 2019). "At pathology, 97.9, 13.7, and 5.3% of schwannomas stained positive for S100, vimentin, and GFAP, respectively." (PMID 29970075, 2018). "The pathological diagnosis was Schwannoma and immunohistochemical testing showed Vimentin (+), S-100 (+), MBP (+), CD56 (+), GFAP (+), Ki-67 (+), Desmin (−), SMA (−), EMA (−), CD34 (positive in tumor vessels)." (PMID 23432938, 2013). "The immunohistological findings confirmed this diagnosis as the tumor cells were positive for S-100 and vimentin, both of which are known to be present in schwannoma." (PMID 23320224, 2012). "Immunohistochemical staining results of other benign schwannomas showed positivity for S‐100,26, 29, 30 SOX10, Vimentin, and GFAP, and negativity for SMA, EMA, CD34, and CD117." (PMID 36440500, 2023). "The immunohistochemistry panel confirmed the diagnosis of neurilemmoma: PS100(+), collagen IV(+), and vimentin(+), but also unveiled a diffuse labelling for glial fibrillary acidic protein (GFAP) in both Antony patterns." (PMID 27446622, 2016). "Schwannomas also stain positively for Leu-7antigen, GFAP, and vimentin." (PMID 34175679, 2021). "The diagnosis of schwannoma is based on immunohistochemical staining of S-100 and vimentin positive and negative results of CD117 and CD34, whereas GISTs are usually positive for CD117, DOG1 and CD34, but S-100 is mostly negative." (PMID 31647020, 2019). "Microscopically, schwannomas are strongly positive for S-100 protein, vimentin and cluster of differentiation 56, however, are negative for other tumor markers." (PMID 25364457, 2014). "Vimentin was expressed in 100% cases and all schwannomas were negative for smooth muscle actin, c-kit, and HMB-45." (PMID 24688535, 2014). "In contrast to gastrointestinal stromal tumors, schwannomas are negative for CD117 and positive for S100 protein and vimentin." (PMID 25360169, 2014). "With reference to the phenotype, the cellular population showed a clear positivity for Vimentin only, being S100 and CD68 negative, which excluded the schwannoma and the MFH, respectively." (PMID 24266985, 2013).
schwannoma (continued). "In contrast to GISTs, schwannomas are consistently negative for CD117 (KIT) and usually negative for CD34, CKs, smooth muscle actin and desmin, but strongly positive for S100 protein and vimentin." (PMID 25360169, 2014).